IL6R (interleukin 6 receptor)
Diseases named in the same sentence as IL6R in open-access papers (continued):
Sharing a sentence is not in itself a finding about the gene and the disease.
rheumatoid arthritis (continued). "Interleukin 6 (IL-6) signaling plays a key role in the pathophysiology of rheumatoid arthritis (RA) and is inhibited by sarilumab, a human monoclonal antibody blocking the IL-6 receptor alpha (IL-6Rα)." (PMID 27716324, 2016). "Tocilizumab is an interleukin-6 receptor inhibitor licensed for moderate to severe rheumatoid arthritis (RA)." (PMID 27818807, 2016). "IL-6R–related diseases like mycosis fungoides, castleman's disease, as well as inflammatory disorders such as rheumatoid arthritis and other cutaneous diseases are currently of interest for PDT and their treatment might be improved by further development of aptamer conjugates in the future." (PMID 24481022, 2014). "Therefore, we speculate that calycosin is a potential candidate as lead compounds for further study in drug development process with IL6R protein against rheumatoid arthritis." (PMID 24991562, 2014). "Currently, two IL-6R monoclonal antibodies (mAbs), Tocilizumab and Sarilumab, are FDA-approved for the treatment of rheumatoid arthritis (RA)." (PMID 39767605, 2024). "IL-6Rα mAb, sarilumab, is also FDA-approved for rheumatoid arthritis and is under clinical investigation in combination with capecitabine for the treatment of metastatic TNBC (NCT04333706)." (PMID 39768178, 2024). "Among three patients with rheumatoid arthritis, we demonstrated a trend towards increased CYP3A4 activity after 3 weeks of anti-IL-6R therapy, which normalized to baseline after 12 weeks of treatment." (PMID 37831074, 2023). "Interestingly, Tocilizumab, a humanized anti-IL-6 receptor (anti-IL-6R) monoclonal antibody, reduces sleepiness in patients with rheumatoid arthritis, which may be related to improvements in sleep quality due to better control of sleep disturbance caused by pain and discomfort." (PMID 35898322, 2022). "Sarilumab is a human monoclonal antibody against interleukin (IL)-6Rα that has been approved for the treatment of adult patients with moderately to severely active rheumatoid arthritis (RA) and an inadequate response or intolerance to one or more disease-modifying antirheumatic drugs (DMARDs)." (PMID 35149777, 2022). "Anti-IL-6 therapy has been met with success in the treatment of rheumatoid arthritis, and mice treated with anti-IL6 and/or anti-IL-6R antibody therapy markedly reduces post-traumatic OA, laying the foundation for its use as a therapy to treat OA." (PMID 36474817, 2021). "Tocilizumab is a humanized monoclonal antibody that targets the interleukin-6 receptor (IL-6R) and has been allowed by the FDA to treat rheumatoid arthritis." (PMID 34884440, 2021). "Another promising nanobody (vobarilizumab/ALX-0061, Ablynx), currently in a phase II trial for treatment of Rheumatoid Arthritis (RA) and Systemic Lupus Erythematosus (SLE), is directed against the Interleukin-6 Receptor (IL-6R)." (PMID 34131806, 2021). "Recent clinical trials with interleukin-6 receptor monoclonal antibody tocilizumab (TCZ) and tumor necrosis factor inhibitors (TNFi) for the treatment of rheumatoid arthritis demonstrated improvements with anti-TNF-α therapy and anti-IL-6 receptor therapy." (PMID 30558178, 2018). "Clinical proof-of-concept of the extended half-life that is obtained in this way has been achieved for an anti-IL-6R and anti-TNF VHH fused to a serum albumin-binding VHH, used in the treatment of rheumatoid arthritis." (PMID 31544807, 2018). "In humans, the IL-6R can be blocked with Tocilizumab, a FDA approved drug for the treatment of several inflammatory diseases, including rheumatoid arthritis." (PMID 27936014, 2016). "So far, no study examined the effect of IL-6R antagonists on periodontitis in patients without rheumatoid arthritis." (PMID 37342352, 2023).
rheumatoid arthritis (continued). "Although the inhibitors of the interleukin-6 receptor (IL-6R) and tumor necrosis factor-α (TNF-α) have achieved a certain success in the clinical treatment of rheumatoid arthritis (RA), great effort should be made to overcome side effects and to improve patient compliance." (PMID 35890412, 2022). "A combination of Sarilumab (antibody targeting soluble and membrane IL-6R; FDA-approved for rheumatoid arthritis) and Capecitabine is currently tested in a clinical trial (EMPOWER; NCT04333706) in triple-negative breast cancer patients (stage I-III, high-risk residual disease)." (PMID 36429126, 2022). "Moreover, IL6R is the target of an FDA-approved therapy (Tocilizumab) for the treatment of several diseases, e.g. rheumatoid arthritis and systemic juvenile idiopathic arthritis." (PMID 36253349, 2022). "Tocilizumab, a humanized monoclonal antibody, selectively targets the interleukin-6 receptor (IL-6r) and is reported safe and effective in other settings such as after chimeric antigen receptor (CAR)-T-cell therapy, rheumatoid arthritis, and giant cell arteritis." (PMID 34002026, 2021). "Therefore, IL-6/IL-6R alterations in schizophrenia may be more closely aligned to vulnerability to infection as well as atopic/contact dermatitis, while IL-6/IL-6R alterations in depression may be more closely aligned to that found in rheumatoid arthritis and cardiovascular disease." (PMID 34280516, 2021). "Presently, however, only two monoclonal antibodies (mAbs), tocilizumab (anti–IL-6R) and siltuximab (anti–IL-6), have been approved in the US for the treatment of rheumatoid arthritis (RA) and Castleman's disease respectively, but not for cancer." (PMID 26840088, 2016). "The anti-IL-6R antibody Tocilizumab has yielded good responses in clinical trials for rheumatoid arthritis and Crohn's disease, but no experiences with Tocilizumab in MS therapy are published." (PMID 24155968, 2013). "Based on results from the open-label use of the IL-6R antagonist tocilizumab (TCZ, Actemra; Roche) for the treatment of GCA and data generated in TCZ trials for rheumatoid arthritis (RA), a phase III randomized, double-blind, and placebo-controlled trial of TCZ for GCA has been initiated." (PMID 23653652, 2013). "Notably, however, in contrast to patients with rheumatoid arthritis, Lp(a) was not modified by IL-6R inhibition by tocilizumab in patients with non-ST-elevation MI (NSTEMI)." (PMID 41543641, 2026). "Tocilizumab is a humanized monoclonal antibody against the IL-6R and is a Food and Drug Administration (FDA) approved drug for the treatment of rheumatoid arthritis (RA), systemic juvenile idiopathic arthritis, giant cell arteritis (GCA), and CRS." (PMID 33717715, 2021). "In this regard, the use of two clinically approved IL-6R antagonists, tocilizumab (TCZ) and sarilumab (SAR), which are currently used for the treatment of rheumatoid arthritis, could be expected to play a crucial part in the treatment for severely ill patients." (PMID 33014208, 2020). "Notably, in untreated rheumatoid arthritis (RA) patients, the expression of ARID5a in CD4+ T cells is enhanced, whereas treatment with the anti-IL6R antibody tocilizumab results in a decrease in the expression of Arid5a, indicating that the IL-6-ARID5A axis may be involved in the pathogenesis of RA." (PMID 36010693, 2022). "Assessing serological inflammation is difficult in tocilizumab (TCZ)-treated rheumatoid arthritis (RA) patients, as standard inflammation parameters, like erythrocyte sedimentation rate (ESR) and C-reactive protein (CRP), are influenced by interleukin-6-receptor inhibition." (PMID 35986420, 2022). "Importantly, the expression of Helios in CD4+ T cells was significantly increased in rheumatoid arthritis (RA) patients who were successfully treated with tocilizumab (TCZ), a humanized anti-IL-6R antibody." (PMID 34257746, 2021).
rheumatoid arthritis (continued). "A small study with 4 ANA‐positive rheumatoid arthritis patients displayed that ANA antibody levels were not affected by IL‐6R blockade 28, but the small patient cohort might not represent a true mirror image of the real picture in SLE, which again demands for further investigation." (PMID 26739431, 2016).
breast carcinoma (87 papers, 2012 to 2026). "Collectively, these results show that WNT5A–IL-6–CCL2 are enriched in TNBC tumors that develop metastasis and that high expression of IL-6R or CCR2 is associated with breast cancer chemoresistance and recurrence." (PMID 37607007, 2023). "In compliance with this result, clinical breast cancer samples analysis confirmed that IL-6R expression was significantly associated with tamoxifen resistance in breast cancer tissues, with high IL-6R expression correlated with poor survival." (PMID 35924148, 2022). "Analysis of clinical breast cancer samples confirmed that IL-6R expression was significantly associated with BQ expression and tamoxifen resistance in primary breast cancer, with high IL-6R expression correlating with poorer survival." (PMID 33806019, 2021). "Multivariate Cox-regression analysis confirmed that high IL-6R expression remained significantly associated with poor overall as well as disease-specific survival in ER+ breast cancer." (PMID 33806019, 2021). "MDA-MB-231 cells are known to express constitutively activated STAT3 pathway, principally through the engagement of an IL-6/IL-6R autocrine loop, and this pathway has been implicated in breast cancer oncogenesis." (PMID 28856117, 2017). "Previously, RECK was shown to be physically associated with IL-6R and gp130 in breast cancer cells." (PMID 37830075, 2023). "In breast cancer, high levels of soluble IL-6R (sIL-6R) in a patient’s sera are likely to be associated with recurrence-free survival when compared to those patients with low levels of sIL-6R." (PMID 36091805, 2022). "Altogether, our results confirmed high expression of IL-6R in ER+ breast cancer was associated with tamoxifen resistance and poorer survival outcome; and IL-6R could be an independent prognostic factor." (PMID 33806019, 2021). "These included SNPs associated with BMI (rs11126666,), breast cancer (rs11552449,), educational attainment (rs7593947,), and kidney function (estimated Glomerular Filtration Rate, rs4014195,), in addition to a variant in IL6R (rs6689306) associated with CAD." (PMID 29227965, 2017). "According to our findings, Syndecan-1 silencing in triple-negative MDA-MB-231 breast cancer cells inhibited proinflammatory signaling via downregulation of relevant receptors and ligands (IL-6/IL6-R/CCL20), which was linked to reduced constitutive activation of NFkB and STAT3." (PMID 24392029, 2013). "Interleukin-6 (IL-6) signalling is a key driver of breast cancer progression, activating pro-survival, pro-inflammatory and metastatic programs through its receptors, IL-6R and GP130." (PMID 42316398, 2026). "Using the provided MFS information in the curated GEO breast cancer patient dataset used in, breast cancer patients were stratified by high versus low tGAS and IL-6/IL-6R/GP130 activation scores." (PMID 39768178, 2024). "Collectively, our results demonstrate that tGLI1 and IL-6/IL-6R/GP130 signaling pathways are frequently co-overexpressed and co-activated and that co-activation is associated with worse MFS in HER2-enriched breast cancer and TNBC." (PMID 39768178, 2024). "Our study demonstrates, for the first time, that co-targeting tGLI1 and IL-6R/GP130/STAT3 signaling pathways is synergistic against HER2-enriched breast cancer and TNBC, warranting future clinical investigations." (PMID 39768178, 2024). "Breast cancer patients with low tGLI1 and IL-6 pathway activity, as indicated by low tGAS and low IL-6/IL-6R/GP130 activation scores, had a prolonged MFS at 55.0 months." (PMID 39768178, 2024). "Using this combined activation signature, we found that tGLI1 and IL-6/IL-6R/GP130 signaling pathways were significantly enriched in HER2-enriched breast cancer (N = 96) and TNBC (N = 166) patients when compared to luminal subtypes (N = 247)." (PMID 39768178, 2024).
breast carcinoma (continued). "Despite recent clinical advancements with anti-IL-6Rα antibodies in breast cancer, mAbs are large, lack BBB permeability, are expensive to develop, and, therefore, are not the best approach for our combination treatments." (PMID 39768178, 2024). "Dysregulated IL-6/IL-6R/GP130 signaling promotes breast cancer cell proliferation, breast CSCs, and therapeutic resistance, contributing to tumor recurrence." (PMID 39768178, 2024). "We proceeded with the TNBC subtype due to a greater increase in tGAS+IL-6/IL-6R/GP130 co-activation in TNBC patients when compared to the HER2-enriched breast cancer subtype." (PMID 39768178, 2024). "Conversely, breast cancer patients with high tGAS and high IL-6/IL-6R/GP130 activation scores had a significantly shortened MFS at a dismal 22.1 months." (PMID 39768178, 2024). "Since dual-targeting tGLI1 and GP130 suppresses metastatic burden and prolongs MFS in vivo, we next wanted to examine the clinical relevance of tGLI1 and IL-6/IL-6R/GP130 in breast cancer metastasis using publicly available patient datasets." (PMID 39768178, 2024). "IL-8R was simulated as the excess receptor because it has been shown to be up-regulated relative to IL-6R in breast cancer, and similar results are shown when for simulations with IL-6R in excess." (PMID 38187701, 2023). "In the case of luminal breast cancer, two meaningful activators have been described: IL-6 receptor (IL-6R) and PRL receptor (PRLR)." (PMID 37834225, 2023). "The screening results showed that none of the receptors for Cx3cl1 (CX3CR1), Cxcl16 (CXCR6), Ccl17 (CCR4, DARC, CCR10) or IL6 (IL6R) was more expressed in basal B compared to basal A or luminal breast cancer cells." (PMID 38055067, 2023). "Down-regulation of IL-6 is linked to a better response to breast cancer treatment and a recent study showed that the IL-6R neutralizing antibody, tocilizumab, abrogated IL-6 signaling in breast cancer." (PMID 36835413, 2023). "Tissue microarrays consisting of breast cancer specimens from a retrospective cohort (n = 850) were stained for IL6R, JAK1, JAK2 and STAT3 via immunohistochemistry." (PMID 37199043, 2023). "In a recent study, a novel developed liposomal nanoparticle loaded with anti-IL6R antibody which deliver to tumor microenvironment achieved a significant effect in inhibiting the metastasis of breast cancer cells in mouse models." (PMID 35924148, 2022). "Overall, modulating IL-6/IL-6Rα interaction shows promising results in all subtypes of breast cancer mediated by IL-6/JAK/STAT3 signaling." (PMID 35371975, 2022). "Clinically, cytoplasmic staining of IL-6Rα is significantly correlated with tamoxifen resistance in ER+ breast cancer patients suggesting IL-6/JAK/STAT3 is an actionable therapeutic target to sensitize tumor cells to current SOC treatment." (PMID 35371975, 2022). "While IL-6Rα mAbs, tocilizumab and sarilumab, have made recent headway in clinical studies for breast cancer, drug repurposing remains an attractive therapeutic strategy to minimize the expensive, time-consuming drug development process." (PMID 35371975, 2022). "This review focuses on emerging studies on the strong linkages of IL-6/IL-6R mediated regulation of inflammation and immunity in cancer, especially in breast cancer." (PMID 35924148, 2022). "The transcription factor C/EBPδ, was reported to be pro-tumorigenic in breast cancer cell lines by directly targeting IL-6R, leading to cancer progression with cancer stem cells activation." (PMID 35924148, 2022). "Among these, we identified as the candidate miR-23c target Interleukin 6 Receptor (IL-6R), whose ligand, IL-6, has been shown to play a pivotal role in breast cancer growth and metastasis." (PMID 35406622, 2022). "Another study showed that IL-6R antagonist Tocilizumab significantly decreases breast cancer stem cell and inhibits tumor growth in Notch3-expressing breast cancers." (PMID 35924148, 2022).
breast carcinoma (continued). "To assess the usefulness of TCZ in overcoming tamoxifen resistance, we first ascertained the expression of IL-6R in breast cancer tissue." (PMID 33806019, 2021). "Immunohistochemistry (IHC) was performed on TMA of primary breast cancer cases to examine the expression of BQ and IL-6R in breast cancer tissues." (PMID 33806019, 2021). "Based on our study, we confirmed that targeting IL-6R should be a possible strategy to reverse tamoxifen resistance in breast cancer." (PMID 33806019, 2021). "Our results highlight the significance of IL-6R in ER+ breast cancer and provides the basis for the development of a novel strategy for reversing tamoxifen resistance in breast cancer." (PMID 33806019, 2021). "Our study illustrates that overexpression of BQ can modulate tamoxifen resistance by enhancing the expression of IL-6 and IL-6R in ER+ breast cancer." (PMID 33806019, 2021). "To provide further in vivo evidence to support our findings, we correlated the expression of BQ and IL-6R in clinical breast cancer samples." (PMID 33806019, 2021). "Several preclinical and clinical studies suggested that IL6R inhibitors, such as Tocilizumab, Sarilumab, and Olamkicept, can be effective in some cancer type including ovarian, pancreatic, breast cancer, and B cell chronic lymphocytic leukemia." (PMID 34576335, 2021). "The protein expression of IL-6R was determined by IHC on TMA of primary breast cancer, and the expression level of IL-6R was shown to be significantly correlated with tamoxifen resistance." (PMID 33806019, 2021). "In breast cancer, the source of IL-30 was stromal leukocytes, and IL-30 stimulated the proliferation of breast cancer cells in a gp130/IL-6R- and STAT1/STAT3-mediated mechanism." (PMID 32023849, 2020). "In breast cancer cells, activation of IL-6/IL-6R signalling suppressed MAOA expression in hypoxic environment." (PMID 32273550, 2020). "When IL-6R is blocked by anti-IL-6R antibody, the metastasis of breast cancer induced by IL-6 is reversed." (PMID 31500658, 2019). "We studied a co-relation among MAO-A and IL-6/IL-6R and tumour angiogenesis/invasion in hypoxic environment in breast cancer model." (PMID 29695771, 2018). "IL-6R siRNA treatment, Dia, and 5-Aza treatment lead to reduced proliferative ability in hypoxic breast cancer cells due to inhibition of IL-6/IL-6R or activation of MAO-A." (PMID 29695771, 2018). "In conclusion, this study validated the rational for targeting IL-6/IL-6R-MAO-A axis for development of novel therapeutic for breast cancer management." (PMID 29695771, 2018). "Suppression of MAO-A by IL-6/IL-6R activation promotes tumour angiogenesis and invasion in hypoxic breast cancer environment." (PMID 29695771, 2018). "Other conditioned medium derived from IL-6R siRNA, Dia, and 5-Aza treated hypoxic breast cancer cells potentially suppressed angiogenesis as confirmed by reduced number of micro blood vessels and tube formation." (PMID 29695771, 2018). "Breast cancer cells were subjected to chemical hypoxia and further transfected with IL-6R siRNA or treated with 5-Aza and Dia." (PMID 29695771, 2018). "Similar effect was also observed due to IL-6/IL-6R inhibition by Dia treatment in hypoxic breast cancer cells." (PMID 29695771, 2018). "Dose dependent Dia (An IL-6/IL-6R signalling inhibitor) treatment was performed in normoxic, as well as hypoxic breast cancer cells." (PMID 29695771, 2018). "Analysing above findings, it can be said that inhibition IL-6R or activation of MAO-A lead to suppression of VEGF in hypoxic breast cancer cells." (PMID 29695771, 2018). "Immunofluorescence of breast cancer cells was performed to evaluate E-Cad expression in hypoxic breast cancer cells and IL-6R siRNA, Dia and 5-Aza treated hypoxic cells." (PMID 29695771, 2018). "Overexpression of both IL-6 and its receptors (IL-6R and sIL-6R) is common in breast carcinoma, oral squamous cell carcinoma and prostate cancer." (PMID 28927416, 2017).